ABO (ABO, alpha 1-3-N-acetylgalactosaminyltransferase and alpha 1-3-galactosyltransferase)
Diseases named in the same sentence as ABO in open-access papers (continued):
Sharing a sentence is not in itself a finding about the gene and the disease.
cancer (continued). "Since the ABO locus is also associated with several other traits and diseases, including lipids, coagulation factors, markers of endothelial function, cardiovascular disease, infectious disease and cancer, we investigated whether other traits available in the UCLEB Consortium are associated with it." (PMID 27280446, 2016). "Here, we present a comprehensive review of the literature evaluating the link between the ABO blood group and cancer." (PMID 28031957, 2016). "Despite these efforts, no meta-analyses have been performed evaluating these modifiers of the ABO blood group phenotypes and more research is needed to understand the role of the blood group antigens in cancer." (PMID 28031957, 2016). "Here, we describe the history and possible functions of the histoblood ABO group and then provide evidence for a role of blood group antigens in the most common cancer types worldwide using both blood type and SNP data." (PMID 28031957, 2016). "Briefly, they suggested that in the early stages of cancer, ABO antigens and Leewis b/y epitopes play an important role in epithelial cell resistance to apoptosis." (PMID 26075384, 2015). "Finally, a possible disequilibrium between the ABO gene and another gene may influence cancer risk." (PMID 24516588, 2014). "ABO blood group antigens are also expressed on cancer cells and can be modified by hypermethylation of the ABO gene promoter, a feature of malignant tumors." (PMID 24516588, 2014). "The ABO promoter region is rich in CpG dinucleotides and previous analysis of this region in several human carcinoma cell lines and cancers has shown that DNA methylation of the ABO promoter region was inversely correlated with gene expression." (PMID 19274076, 2009). "In the future, ABO antigens could be an indicator of preneoplastic transformation and cancer progression as well as a useful economic prognostic factor for guiding adjuvant therapy." (PMID 39132152, 2024). "The results indicate that SURF1 may have a pro-oncogenic role in cancer, whereas ABO may have oncogenic properties." (PMID 38706896, 2024). "The ABO blood group antigens and the rhesus factor could impact the cancer progression and survival via various mechanisms." (PMID 36181128, 2022). "In all, ABO blood types on prognosis of different cancers are still controversial." (PMID 36181128, 2022). "The normal ABO antigen is lost in cancer patients, and new tumor antigens are acquired." (PMID 31777587, 2019). "The expression of BG antigens on cancer cells can be subject to genetic and epigenetic modifications, e.g. ABO promotor methylation, which in turn might be related to tumor invasion and metastasis." (PMID 29596526, 2018). "Several studies recently described the involvement of the ABO blood group in the pathogenesis of many human disorders, including cardiovascular disease and cancer, so that its clinical significance extends now beyond the traditional boundaries of transfusion medicine." (PMID 25592962, 2015). "However, altered expression of ABO and Lewis antigens is related with prognosis in carcinoma types." (PMID 38863964, 2024). "In the present study, which included all patient stages, we could not find an association between the ABO blood type and cancer mortality." (PMID 22911869, 2012). "Elevated methylation levels of ABO were discovered in individuals with BRCA, relative to the control group, suggesting a potential involvement of ABO as an oncogene in cancer development." (PMID 38706896, 2024). "This was accomplished by employing transcriptomics techniques to examine the functions of ABO and SURF1 in cancer." (PMID 38706896, 2024). "Additional investigation into the functions of ABO and SURF1 in cancer has yielded noteworthy findings." (PMID 38706896, 2024). "Here, we highlight two interesting examples, ABO and WNT3, both are shared by COVID-19 with more than one investigated cancer." (PMID 37636041, 2023).
cancer (continued). "Further experimental studies are also needed to unravel the molecular mechanisms linking ABO blood type, VWF, and cancer development." (PMID 25592962, 2015). "Combining the results of this study, we speculate that MUC1-rs4072037 and ABO-rs1053878 may affect the expression level of CA153, thereby affecting the occurrence and development of cancer." (PMID 35144566, 2022).
tumor (35 papers, 2004 to 2025). "Previously, researchers have shown that the ABO antigen’s affiliation, beyond its necessity in daily transfusion medicine, constitutes an independent risk factor of cardiovascular diseases, neoplasm development, and infections." (PMID 35366247, 2021). "Aberrant ABO antigens have been found on tumor tissues compared to normal cells, such as loss of the A or B epitope and accumulation of the H antigen, or incompatible expression of A antigens by tumors in subjects with blood type O." (PMID 28448592, 2017). "The tumor microenvironment is characterized by an immunosuppressive milieu 40, and the immunoassay results indicated that ABO is linked to cytotoxicity, helper T-cell 2 (Th2), central memory, follicular helper T-cells (Tfh), natural killer (NK) cells, and CD4+ T-cells in BRCA." (PMID 38706896, 2024). "In addition, we examined the association between the ABO blood group and tumor grade, clinical stage of disease (NMI, MI, M), and incidence of disease recurrence in NMI tumors." (PMID 39040623, 2024). "Many studies aiming to reveal the association between the ABO blood groups and various diseases revealed that ABO system might play an important role in the pathogenesis of immunological, cardiovascular, and neoplastic diseases." (PMID 33936883, 2021). "Thus the degree of loss of ABO (H) antigens in tissue specimens can be used as a marker of the tumour stage of the patient." (PMID 32334486, 2020). "As ABO genes encode glycosyltransferases, which are involved in signaling and intercellular adhesion, it has been suggested that these functions promoting local tumor implantation might be altered based on the specific blood group." (PMID 39320512, 2024). "ABO promoter methylation analysis revealed high methylation levels in various types of tumor cell lines and clinical patient specimens." (PMID 39355843, 2024). "Several findings suggested that the structure of certain tumor antigens is similar to that of ABO antigens." (PMID 37296868, 2023). "Here, we prove through experiments that tumours expressing ABO blood group antigens can be used as a new strategy for the treatment of solid tumours." (PMID 34376742, 2021). "Since the difference in the EEL signals between the tumor and non-tumor regions was large, with the absolute log2 fold change (|FC[log2]|; tumor/non-tumor ratio) of 2.9, we further analyzed the other lectins recognizing ABO blood group antigens." (PMID 32232009, 2020). "The expression of blood group A, B, and H glycosphingolipids was in agreement with the ABO phenotype of the patients, and the relative amounts of the glycosphingolipids with blood group determinants were different in the three tumour samples." (PMID 33168837, 2020). "The expression of ABO blood antigens on tumor cells was influenced by hyper-methylation of ABO promoter, which was associated with the tumor progression." (PMID 31777605, 2019). "To better understand the possible role of the ABO blood group in tumorigenesis, we review the data for the most common tumor types worldwide." (PMID 28031957, 2016). "Overall, we have identified ABO blood type, along with tumor stage, tumor site, BMI, Hb level, and previous use of anticoagulation medication as predictors for risk of TE in PC." (PMID 26275671, 2015). "However, free-glycans with ABO-antigens were unreliable as tumor marker candidates because there was significant variability in the level of these glycans across only a small number of patients." (PMID 35318379, 2022). "In addition, some researches have shown that the structure of certain tumor antigens was similar to the structure of antigens of ABO blood group system." (PMID 32093636, 2020). "Considering this pancreas-specific association, the present results may highlight the significance of ABO blood groups on glycoproteins in the tumor pathophysiology." (PMID 32232009, 2020). "LOH at 9q34, in which the ABO gene is located, was also a frequent event in these tumours." (PMID 15226771, 2004).
tumor (continued). "Therefore, these molecules may provide a biological basis for the postulated influence of ABO blood types on OS of patients, by directly linking ABO blood group, tumor initiation and tumor spread." (PMID 36181128, 2022). "In tumor tissues, the expression of ST3GAL6 was found to be notably reduced, whereas the expression levels of B3GALT2, ABO FUT3, B3GNT3, and B3GNT5 were observed to be significantly elevated." (PMID 37781041, 2023). "Taken together, these results suggest that patients with blood group A may have diminished tumor immune response due to the reduced ability of the immune system to recognize and attack tumor cells expressing antigens that are structurally similar to the ABO antigen." (PMID 37296868, 2023). "The lectins recognizing ABO blood group antigens such as DBA, PTL-I, and EEL were extracted for the non-tumor samples." (PMID 32232009, 2020). "Notably, the seven lectins recognizing ABO blood group antigens (EEL, DBA, PTL-I, GSL-I-A4, GSL-I-B4, UEA-I, and TJA-II) were detected almost exclusively in the non-tumor regions, as is the case in the tissue glycomic profiles." (PMID 32232009, 2020). "Notably, the signals of several lectins for ABO blood group antigens (EEL, DBA, PTL-I, UEA-I, and TJA-II) were detected only in the non-tumor regions, suggesting this is a PDAC-relevant alteration in the tissue glycome." (PMID 32232009, 2020). "Hypermethylation targets only the ABO locus, but not surrounding genes, which suggests that hypermethylation is a specific tumor-related event." (PMID 32334486, 2020). "Another hypothesis is that the ABO gene is directly related to the level of circulating inflammatory mediators (e.g., TNF-α, E-selectin, or P-selectin) that play a role in the local inflammatory tumor environment." (PMID 39320512, 2024). "However, epithelial cells such as colorectal epithelial cells that normally do not express ABO antigens on their surfaces show their expression in tumor formations." (PMID 26075384, 2015).
cardiovascular disease (28 papers, 2013 to 2025). "Recent studies have established the association of six genetic variants of the ABO gene with a high prevalence of different cardiovascular diseases, including ACS, in different populations, the rs579459 T/C, rs8176746 T/G, rs512770 T/C, rs495928 T/C, rs651007 T/C, and rs8176740 A/T." (PMID 37334748, 2023). "Considering the potential impact of ABO groups on cardiovascular diseases, we hypothesized that the ABO gene polymorphisms are associated with the incidence of ACS, and with plasma lipid profile in the Mexican population." (PMID 37334748, 2023). "The ABO gene has been linked to cholesterol absorption and cardiovascular disease." (PMID 32174972, 2020). "Other examples include artery eQTL for the cardiovascular diseases associated gene PHACTR1 (P = 8 × 10−10); the lysosomal acid lipase (LIPA) gene and microglia eQTL (P = 2 × 10−11); and the ABO blood group gene with plasma pQTL (P = 1 × 10−21)." (PMID 39563277, 2024). "Both ABO and PALMD are widely expressed in tissues, and both harbor variants associated with cardiovascular disorders." (PMID 37884687, 2023). "Yet, the study still highlights the significance of the ABO gene as well as its role in cardiovascular disease, although the mechanisms involved are left for future studies to discover." (PMID 37270590, 2023). "Further studies will be required to define whether inter-individual variations in ABO(H) expression on platelets and/or VWF (particularly HXP and LXP) impact upon risk for cardiovascular disease." (PMID 33110150, 2020). "That publication attributed on the ABCG8 and ABO alleles did not correlate risk of cardiovascular disease with cholesterol synthesis, measured by the lathosterol/cholesterol ratio, but only with the elevation of intestinal cholesterol absorption, measured by the cholestanol/cholesterol ratio." (PMID 32579186, 2020). "In cardiovascular diseases, the genes FBRSL1, IL10RB, ACE2 and ABO were those that were outstanding." (PMID 36430729, 2022). "The linkage between cardiovascular disease/cardiovascular mortality and having a non-O blood type through structural variation in the ABO gene is a correlation that has not been thoroughly explained." (PMID 37270590, 2023). "The role of ABO gene products in cardiovascular disease is not fully understood." (PMID 31690775, 2019).
infectious disease (22 papers, 2015 to 2025). A disorder directly resulting from the presence and activity of a microbial, viral, or parasitic agent in humans. "As mentioned, previous studies have demonstrated that ABO and Rh blood groups can influence susceptibility to various infectious diseases." (PMID 41303137, 2025). "In 1901, Karl Landsteiner discovered the ABO blood group system, which has been linked to various infectious diseases such as Helicobacter pylori, Plasmodium falciparum, norovirus, hepatitis B virus, SARS-CoV, and MERS-CoV." (PMID 34721388, 2021). "The ABO blood group has been previously found to contribute to the risk of multiple infectious diseases in a series of studies." (PMID 32793517, 2020). "Genetic and environmental factors, including genetic drift, population migration, and regional variation in exposure to infectious diseases, may significantly influence allele frequencies and ABO blood group distributions." (PMID 40845133, 2025). "Moreover, the association between the ABO system and the frequency of certain infectious diseases can also be affected by the presence of iso-hemagglutinins." (PMID 37442822, 2023). "Moreover, a couple of studies related to the ABO phenotype present links between genetically determined human ABO blood groups with increased risk of various infectious diseases." (PMID 35735664, 2022). "The results of the current study findings could potentially promote the implementation of an additional layer of health surveillance and infectious disease control, by further defining the most at-risk populations vis-à-vis their ABO and Rh status, in addition to currently accepted risk factors." (PMID 37964217, 2023). "First, the al-PRP was prepared with ABO and Rh matched blood using platelet concentrate from a blood bank ensuring processing under sterile conditions and ruling out infectious diseases." (PMID 34945062, 2021). "Furthermore, it was suggested that different prevalence of ABO blood group genotypes among various populations could be associated with selective pressure of some infectious diseases, particularly of the infections with Plasmodium falciparum and Vibrio cholera." (PMID 33936883, 2021). "The applied MALDI-TOF MS and MS/MS strategy presented here allowed for the characterization of glycans bearing the ABO(H) blood group antigens which, like genetic factors, are involved in several hemostasis-related diseases and in many infectious diseases." (PMID 34360826, 2021). "As a genetic factor, the ABO blood type distribution has been extensively investigated in the field of infectious diseases." (PMID 33407977, 2021). "Many studies have found that the ABO blood group plays an important role in various human diseases, such as cardiovascular, oncological, and some infectious and non-infectious diseases." (PMID 32793517, 2020). "Furthermore, several studies have investigated the relationship between the ABO(H) blood group distribution and the occurrence of some infectious diseases, such as HIV, malaria, influenza, and, recently, the COVID-19 pandemic." (PMID 34360826, 2021). "The question arises whether the increased risk of severe infectious diseases in rituximab induced ABOi recipients might be avoided by a lower rituximab dosage without increasing the risk of posttransplant anti-ABO titer rebound and AMR." (PMID 41459482, 2025).
hematologic malignancies (9 papers, 2009 to 2024). "DNA methylation of the ABO promoter would explain much of the reported loss of ABH antigens in patients with hematological malignancies." (PMID 19274076, 2009). "We have found that loss of ABH antigens in patients with hematological malignancies is associated with a corresponding loss of ABO allelic expression in a significant proportion of patients." (PMID 19274076, 2009). "However, we show that DNA methylation is significantly associated with silencing of the ABO transcript in patients with hematological malignancies and that the ABO transcript can be re-expressed in leukemic cell lines by treating with a demethylating agent." (PMID 19274076, 2009). "In hematologic malignancies, the blood group antigens that undergo ABO antigen change are reverted to the original blood group after disease remission." (PMID 38654809, 2024). "In this study, we investigated the frequency and phenotypes of blood groups (ABO, Kell, Duffy, Rh) in patients with hematologic malignancies." (PMID 36861861, 2023). "We set out to determine whether LOH and/or DNA methylation of ABO was responsible for ABH antigen alterations in patients with hematological malignancy." (PMID 19274076, 2009). "In this study, we evaluated the impact of ABO compatibility and incompatibility on outcomes and complications related to hematopoietic stem cell transplantation (HSCT) performed for various hematological disorders at our center." (PMID 37859904, 2023). "In the current study, we illustrate our experience in terms of the outcomes and complications observed due to ABO compatibility and incompatibility in hematopoietic stem cell transplantation (HSCT) performed for various hematological disorders at our center." (PMID 37859904, 2023).
kidney (2 papers, 2023 to 2024). "First, we examined the presence of ABO antigens in renal biopsy specimens acquired from kidney transplant recipients." (PMID 38436899, 2024).
kidney disease (2 papers, 2018 to 2022). "Since secretor status determines the ability to secrete blood group antigens, we also explored the impact of ABO blood group on associations observed for mumps infection and kidney disease." (PMID 30345375, 2018).
adenocarcinoma (1 paper, 2012). A common cancer characterized by the presence of malignant glandular cells. "SNP rs505922, located within the first intron of the ABO gene, has been associated with the adenocarcinoma subtype of pancreatic cancer." (PMID 22642827, 2012).
bacterial infection (1 paper, 2024). "This cohort study evaluates the risk of bacterial infection onset at 7, 30, and 90 days after birth of neonates with dissimilar ABO blood group from their mother." (PMID 39476233, 2024). "Accordingly, the current study aimed to ascertain the association between maternal-newborn ABO blood group incongruence and lower risk of bacterial infection in newborns." (PMID 39476233, 2024). "The primary outcome of bacterial infection within 30 days of birth occurred in 328 (8.6 per 1000) newborns in the incongruent ABO blood group compared with 1029 (10.3 per 1000) newborns in the congruent group." (PMID 39476233, 2024). "In a previous study, we found that ABO blood group incongruence between a mother and newborn is associated with protection against serious bacterial and viral infections, but details of the type and anatomical location of those bacterial infections are lacking." (PMID 39476233, 2024).
gastrointestinal tract cancers (1 paper, 2020). "The ABO blood group has been found to be associated with the risk of multiple malignancies, including gastrointestinal tract cancers 41 and liver cancer." (PMID 33173428, 2020).